CCL2 (C-C motif chemokine ligand 2)
Diseases named in the same sentence as CCL2 in open-access papers (continued):
Sharing a sentence is not in itself a finding about the gene and the disease.
Alzheimer disease (116 papers, 2005 to 2026). A progressive, neurodegenerative disease characterized by loss of function and death of nerve cells in several areas of the brain leading to loss of cognitive function such as memory and language. "The CCL2-2518-A/G polymorphism has been extensively studied and proven to be a risk factor for Alzheimer’s disease." (PMID 36865551, 2023). "Elevated CCL2 has been detected in the cerebrospinal fluid (CSF) of patients with Alzheimer’s disease (AD) and HIV-associated neurocognitive disorder (HAND)." (PMID 32103758, 2020). "Additionally, CCL2 expression has been associated with the development of neurological disorders such as multiple sclerosis, Alzheimer's disease, and Parkinson's disease." (PMID 40548298, 2025). "Neuroinflammatory pathways and specifically the CCL2—CCR2 axis could be determinant factors in identifying new targets that aim at reducing the common underlying pathology in Alzheimer's disease and dementia-related tauopathies." (PMID 32508844, 2020). "Moreover, glutaminyl cyclase contributes to the pathogenesis of both Alzheimer’s disease and fatty liver disease and pyroglutamate formation of CCL2 has been suggested as a possible underlying mechanism in both diseases." (PMID 28178200, 2017). "Indeed, MCP-1/CCL2 has been used as a biomarker for neurological diseases associated with infection, and correlates to faster cognitive decline in prodromal Alzheimer’s disease." (PMID 26151848, 2015). "CCR2 and its main ligand CCL2 (MCP-1) might also be involved in the altered metabolism of beta-amyloid (Aβ) underlying Alzheimer's disease (AD)." (PMID 22303443, 2012). "Given the critical role of CCL2 in the proinflammatory process and its implication in neuroinflammation underlying the pathogenesis of certain CNS diseases, e.g., Alzheimer’s disease, it is postulated that the elevated CCL2 levels observed in the present study may indicate neuroinflammation in ASD." (PMID 28167942, 2017). "Patients with MCI and mild Alzheimer’s disease exhibited elevated serum CCL2 and cerebrospinal fluid levels, which likely represents an early event in the pathogenesis of Alzheimer’s disease, far preceding the clinical onset of the disease." (PMID 37373554, 2023). "In Alzheimer’s disease, CCL2 is primarily expressed by microglia and macrophages, which are involved in β-amyloid removal, myelin degradation, and neuronal loss." (PMID 37373554, 2023). "Upregulation of CCL2 has also been shown in the cerebrospinal fluid (CSF) from patients with neurodegenerative diseases including mild cognitive impairment and Alzheimer’s disease." (PMID 36551169, 2022). "Our previous studies indicate that CCL2 plays a relevant role in the progression of Alzheimer’s disease." (PMID 35328727, 2022). "In mice, peptides from milk reduced the expression of inflammatory factors such as TNF-α, monocyte chemoattractant protein-1 (MCP-1/CCL2) or inducible nitric oxide synthase (iNOS) in the hippocampus in a model of Alzheimer’s disease." (PMID 33801489, 2021). "Oral administration of a bioactive milk tripeptide inhibits the expression of inflammatory factors such as TNF-α, CCL2 or iNOS in the hippocampus of the Alzheimer’s disease mice model." (PMID 33801489, 2021). "CCL2 is an important member of the CC chemokine family which plays a crucial role in multiple CNS diseases, including stroke, epilepsy, Alzheimer's disease (AD), cognitive impairment, and HAND." (PMID 32185196, 2020). "We next wanted to compare CCL2 levels and the differential brain region response, to a similar neurodegenerative disease, Alzheimer’s disease (AD)." (PMID 33278887, 2020). "Elevated circulating levels of CCL2 have previously been shown in a number of other neuroinflammatory disorders such as ischemic stroke, Alzheimer’s disease, and traumatic brain injury." (PMID 25012628, 2014).
Alzheimer disease (continued). "Increases in IL-6, CCL2 and CXCL8 are associated with activation of perivascular macrophages and glia, and with the development of neurological diseases such as HAND, Alzheimer’s disease, Parkinsons’s or Huntington’s disease, and multiple sclerosis." (PMID 22901451, 2012). "Nevertheless, their physiologic role could degenerate into neurotoxic effects during chronic neuroinflammation, as demonstrated in a murine model of Alzheimer’s disease for CCL2/CCR2 and CXCL1/CXCR2." (PMID 40801605, 2025). "Based on this observation, and on the impaired resolution of inflammation known to occur in Alzheimer’s disease, we decided to analyze whether CCL2 modulates the resolution of inflammation in the brain." (PMID 35328727, 2022). "This suggests that, in inflammatory conditions such as the ones that partially resemble Alzheimer’s disease in 5xFAD mice, CCL2 may exert a repressive effect on the expression of these enzymes." (PMID 35328727, 2022). "In agreement with this, our previous studies allowed us to observe that the genetic suppression of CCL2 in the 5xFAD mouse model of Alzheimer’s disease reduces the accumulation of amyloid β plaques, the production of pro-inflammatory mediators and the neuronal damage." (PMID 35328727, 2022). "Based on this, we decided to analyze whether the accumulation of CCL2 modifies the processes involved in the resolution of inflammation in glial cells, which seem to play a key role in the progression of Alzheimer’s disease." (PMID 35328727, 2022). "Of note, both CXCL8 and CCL2 levels were found to be increased in the cerebrospinal fluid and brain tissue of Alzheimer’s disease patients and higher CCL2 levels in cerebrospinal fluid were associated with a faster rate of cognitive decline during the early stages of the disease." (PMID 34335238, 2021). "However, recent studies have revealed that CCL2 is also involved in several central nervous system (CNS) diseases, such as epilepsy, Alzheimer’s disease, and ischaemic brain injury." (PMID 32103758, 2020). "Early intraneuronal accumulation of toxic amyloid in a mouse model of Alzheimer’s disease was recently shown to initiate inflammatory gene expression of chemokines CCL2 and CCL3 in pyramidal neurons of the hippocampus, thus demonstrating that neurons have the capacity to initiate such signaling." (PMID 32943056, 2020). "Moreover, CCL2 has been shown to be induced and involved in various neurodegenerative disorders including Alzheimer’s disease, multiple sclerosis, and ischemic brain injury (Semple, Kossmann & Morganti-Kossmann, 2010)." (PMID 31915578, 2020). "AAV2/1 has been utilized to target neurons for anti-inflammatory effects of dominant-negative chemokine CCL2 mutant, interleukin-10 (IL-10) in mouse models of Alzheimer’s Disease (AD) and brain-derived neurotrophic factor (BDNF) in rat models of Huntington’s Disease." (PMID 29244806, 2017). "Second, CCL2 is expressed in brain astrocytes in pathological conditions, such as experimental autoimmune encephalomyelitis, brain ischemia, traumatic brain damage, and Alzheimer’s disease." (PMID 22721162, 2012). "Among them, CCL2 is the most potent activator of CCR2 signaling, and the upregulation of CCR2 by CCL2 is associated with cancer metastasis, relapse, and inflammatory diseases in the central nervous system, including multiple sclerosis, Alzheimer’s disease and ischemic stroke." (PMID 35570218, 2022). "Authors hypothesized the key role for CCL2 in Alzheimer’s disease pathogenesis." (PMID 33333870, 2020). "MIP-1b (CCL4), IL-8 (CXCL8), and MCP-1 (CCL2) have all been identified as pro-inflammatory chemokines and can induce the migration of leukocytes to a desired site and have also been implicated in other inflammatory diseases such as multiple sclerosis, Alzheimer's disease, and HIV." (PMID 22359672, 2012).
Alzheimer disease (continued). "Our results highlight a shared neuroinflammatory signature across Alzheimer’s disease (AD), Parkinson’s disease (PD), and Huntington’s disease (HD), characterized by the dysregulation of hub genes such as MMP9, S100A8, S100A9, CCL2, and LCN2." (PMID 41614741, 2025). "CCL2 and its receptor CCR2 are induced and take part in a multitude of neurodegenerative diseases like Alzheimer’s disease, multiple sclerosis, and ischemic brain injury." (PMID 35246016, 2022). "In a mouse model of Alzheimer's disease, peptides from milk reduced the expression of inflammatory factors such as TNF-α, monocyte chemoattractant protein-1 (MCP-1/CCL2) inducible nitric oxide synthase (iNOS) in the brain." (PMID 34888336, 2021). "In a study on Alzheimer’s disease, downregulation of PU.1 in BV2 cells suppressed the expression of pro-inflammatory genes, such as CCL2 and IL-1β, as well as Aif1 (also known as Iba1), a molecular marker of microglia." (PMID 34681723, 2021). "Based on former reports, CCL2 and CCL4 were thought to promote inflammation in the models of Alzheimer’s disease, while IL23 inhibits inflammation." (PMID 29959371, 2018). "Monocyte chemoattractant protein-1 (MCP-1, also known as chemokine CCL2) is a vital chemokine that mediates inflammation in Alzheimer’s disease (AD)." (PMID 29352259, 2018). "It has been shown that CCL2/CCR2 signaling is upregulated and plays a role in the pathogenesis of neurodegenerative disorders, such as Alzheimer’s disease, multiple sclerosis, HAND, and in the experimental autoimmune encephalomyelitis, a murine model for inflammatory demyelinating diseases." (PMID 34764955, 2021). "An Alzheimer’s disease (AD) mouse model based on GSK3β overexpression is characterized by severe brain inflammation, e.g., increased numbers of activated microglia and enhanced TNF, IFN-γ, MIP-1α, -3α, and CCL2 (but also IL-10) expression." (PMID 32231133, 2020). "In the researches of Alzheimer’s disease (AD) and HIV dementia it was found that CCL2 could accelerate the decline of cognitive function, leading to the formation of dementia, indicating that CCL2 may be related to cognitive dysfunction." (PMID 28870240, 2017). "In models of Alzheimer disease produced by overexpression of APP/PS1 or human APP, CX3CR1 knockout results in decreased levels of pro-inflammatory cytokines Tumor Necrosis Factor (TNF) and monocyte chemotactic protein 1 (CCL2) but increased Interleukin 1-beta (IL1β)." (PMID 26469270, 2015). "However, CCL2 does not seem to activate these cells directly, and genetic CCR2 deletion has been proven to facilitate the progression of neurodegeneration in different mouse models of Alzheimer’s disease." (PMID 35328727, 2022).
pancreatic cancer (114 papers, 2010 to 2026). "At the transcript level, mRNA expression of Ccl2, Ccl7, Cxcl1, Cxcl3, and Csf2 was markedly downregulated in Ccn1‐deficient pancreatic tumors, whereas Cxcl5, Csf1, and Csf3 expression remained unchanged, and Ccl20 mRNA was elevated." (PMID 40287974, 2025). "In a study examining serum CCL2 levels in 68 patients with pancreatic cancer, a high level of serum CCL2 was strongly associated with poor survival and prognosis." (PMID 33297571, 2020). "CCL2 was found to be a ubiquitously expressed gene, including expression in adipose tissue, skeletal muscle, and pancreatic cancer cells, and was associated with cachexia in pancreatic cancer patients." (PMID 33297571, 2020). "CCL2 and IL-8 cytokine levels were found to be associated with poorer survival after pancreatic resection in a study analyzing the sera of 85 pancreatic cancer patients and 23 patients with benign pancreatic tumors." (PMID 33297571, 2020). "Proinflammatory chemokine MCP1 (aka C‐C Motif Chemokine Ligand 2 or CCL2) is shown to recruit tumor‐associated macrophages for creating an immunosuppressive tumor microenvironment in pancreatic cancer." (PMID 29573228, 2018). "In addition, high CCL2 expression within pancreatic tumors is associated with reduced infiltration of CD8+ T cells and poor survival." (PMID 30776148, 2019). "Furthermore, an enhanced expression of CCL2 is associated with poorer survival in pancreatic cancer." (PMID 27367029, 2016). "In pancreatic cancer, high CCL2 expression is associated with significantly decreased survival." (PMID 26294325, 2015). "Research has shown that pancreatic cancer cells recruit and reprogram macrophages through the CCL2/CCR2 signaling pathway, leading to the subsequent release of TWEAK via the CCL5/TRAF6/NF-κB pathway." (PMID 39972459, 2025). "A therapeutic approach targeting ENSA-K63la or CCL2 has shown promise in sensitizing pancreatic cancer immunotherapy." (PMID 39883522, 2025). "In pancreatic cancer, it has been shown that tumor cells begin secreting CCL2 soon after malignant transformation, acting as a potent chemoattractant for monocytes and macrophages." (PMID 40282185, 2025). "Human pancreatic cancer tumors produce CCL2, which attracts immunosuppressive CCR2+ monocytes that infiltrate the tumor microenvironment and differentiate into TAMs." (PMID 40243455, 2025). "Taken together, these findings suggest that TMBIM1 promotes pancreatic cancer cell proliferation and migration through mechanisms involving CCL2." (PMID 40083936, 2025). "Investigations into pancreatic cancer have revealed that both CCL2 and MMP13 are regulated by the upstream IFN-γ/STAT1 signaling, which facilitates macrophage polarization." (PMID 40909948, 2025). "MMP-2 contributes to cancer-nerve crosstalk in breast, prostate, and pancreatic cancers, whereas neural cell secretion of CCL2 is a contributor to cervical, prostate, and pancreatic cancer PNI." (PMID 40160208, 2025). "A reduction in tumor-promoting macrophage markers such as Arginase 1 (Arg 1) and CCL2 was also observed in BMDMs stimulated with conditioned media from pancreatic cancer cells and treated with I-BET-762." (PMID 39337472, 2024). "Accordingly, we showed in pancreatic cancer cells (KPC) in vitro an induction of monocyte/macrophage-chemoattractant cytokines such as CCL2/MCP1, CCL20/MIP3α, CXCL2/MIP2α and also GM-CSF by Juzentaihoto (and the combination)." (PMID 39723364, 2024). "Blockade of the CCL2/CCR2 axis decreased tumor-infiltrating inflammatory monocytes–macrophages but increased T cell infiltration in a murine pancreatic cancer model." (PMID 38402307, 2024). "Here, we detected increased CCL2 protein immunoreactivity in the nerves of pancreatic tumors of TPAC mice compared with KPC." (PMID 37607005, 2023). "For instance, the fibroblasts-derived CSF-1, IL-6 and CCL2 has been found to promote macrophages infiltration and M2 phenotype polarization process in pancreas cancer." (PMID 37325617, 2023).
pancreatic cancer (continued). "To find out the potential role of CCL2 in NI in our GEMMs, we analyzed CCL2 content in the nerves within primary pancreatic tumors from KPC and TPAC mice." (PMID 37607005, 2023). "The results showed some of the frequently cited inflammatory biomarkers for breast and pancreatic cancers included IL-6, IL-8, CCL2, CD8+ T cells and VEGF." (PMID 37181043, 2023). "In a previous study, we showed that pancreatic cancer cells (murine cell line PDA6606) release high amounts of CCL2." (PMID 37371612, 2023). "CCL2 activates the cancer cell cytoskeleton and enhances the migratory properties of pancreatic cancer cells via CCR4." (PMID 37607005, 2023). "In mouse melanoma and pancreatic cancer models, knockdown of CCL2 with siRNA or antibody neutralization effectively inhibited DC recruitment, reduced CD68+ macrophage infiltration, and decreased tumor growth and metastasis." (PMID 35702353, 2022). "Independently, CCL2 was reported to recruit monocytes and reduce CD8+ T cell infiltration in pancreatic tumors, and CCL2 inhibition and monocyte neutralisation increased the sensitivity of PDAC to immune checkpoint blockade." (PMID 36497150, 2022). "Another study demonstrated that HDAC5 recruited macrophages to the tumor microenvironment through the Suppressor of cytokine signaling 3 (Socs3)/C-C motif chemokine ligand 2 (CCL2) axis and promoted pancreatic cancer via TGF-β-dependent paracrine signaling." (PMID 34178647, 2021). "Previous reports of radiation in mouse models of pancreatic cancer revealed an increase in immunosuppressive monocytes recruited by CCL2, and combination therapy modestly increased the frequency of tumour-infiltrating monocytes." (PMID 34784792, 2021). "The cytokine MCP‐1 (Ccl2) signals macrophage and monocyte migration and infiltration and was recently identified as a prognostic marker in pre‐cachectic pancreatic cancer patients." (PMID 33956410, 2021). "For example, the high-density of the ECM in breast and pancreatic cancers activates tumor cells and CAFs that secrete the monocyte cytokines CCL2 and colony-stimulating factor 1 (CSF-1)." (PMID 33066357, 2020). "On the other hand, in resected pancreatic cancer patients, CCL2 is an independent favorable prognostic factor with indirect effects on pancreatic cancer cell growth via cytokines, such as IL1B." (PMID 32429318, 2020). "A study of 212 pancreatic cancer patients found that CCL2 serum levels in pancreatic cancer patients were significantly higher than in normal healthy subjects." (PMID 33297571, 2020). "An analysis of 483 pancreatic cancer patients showed that patients with pancreatic cancer with high CCL2 expression and low CD8+ T lymphocyte infiltration had significantly reduced survival." (PMID 33297571, 2020). "Carlumab, monoclonal antibody directed against CCL2, was tested in pancreatic cancer patients but needs further studies to assess its impact on macrophages, as the number of patients enrolled in the trial were less." (PMID 30925924, 2019). "The overexpression of heparanase in these pancreatic tumors also led to increased macrophage expression of IL-6, IL-10, C-C motif chemokine ligand-2 (CCL-2), vascular endothelial growth factor (VEGF) and macrophage scavenger receptor-2 (MSR-2)." (PMID 31110966, 2019). "The CCL2/CCR2 axis has prognostic significance in pancreatic cancer and was suggested as an effective immunotherapeutic target for a novel CCR2 inhibitor (PF-04136309)." (PMID 30925924, 2019). "We similarly profiled CM from primary pancreatic tumor associated stromal (TAS) cells, which secreted very high levels of EGF (4337 pg/mL) and MCP-1/CCL2 (4,951 pg/mL), moderate levels of IL-8 (70.94 pg/mL), and low levels of GRO (18.65 pg/mL)." (PMID 31769424, 2019). "Applying radiotherapy on KPC pancreatic carcinoma also leads to a significant increase in CCL2 production by tumor cells." (PMID 31474975, 2019).